RNU6-419P (RNA, U6 small nuclear 419, pseudogene)
Gene: Small nuclear RNA gene on chromosome 14 (73,246,818 to 73,246,880, reverse strand). Ensembl gene ENSG00000252839.
Homologues: Orthologues: chimpanzee U6 (100% identical), rabbit U6 (87% identical), guinea pig U6 (71% identical). Paralogues in human: RNU6-1316P (92% identical), RNU6-16P (92% identical), RNU6-29P (92% identical), RNU6-36P (92% identical), RNU6-1 (90% identical), RNU6-1104P (90% identical), RNU6-1145P (90% identical), RNU6-11P (90% identical), RNU6-1209P (90% identical), RNU6-2 (90% identical), RNU6-20P (90% identical), RNU6-25P (90% identical), and 1286 more.